MTOR (mechanistic target of rapamycin kinase)
Diseases named in the same sentence as MTOR in open-access papers (continued):
Sharing a sentence is not in itself a finding about the gene and the disease.
tumor (continued). "Sox2 is a pluripotency factor that regulates HNSCC CSC fate through a PI3K/mTOR/Sox2/ALDH axis, which generates a tumor-initiating population with the capacity for asymmetric division and proliferation." (PMID 30275505, 2018). "Simultaneous treatment of the mTOR/ALK-positive graft with rapamycin and crizotinib was more effective than rapamycin as mono-drug: tumor shrinkage in four and growth stagnation in one of five MPM tumors was achieved." (PMID 29755689, 2018). "Here, we focus on FBXW7, a bona fide tumor suppressor that restrains EMT and directly target mTOR for ubiquitin degradation in NSCLC." (PMID 29633504, 2018). "Besides, NDRG2 protection on photoreceptor cell viability might also be due to mechanisms such as maintained autophagy, for which certain NDRG is involved in the autophagic mammalian target of rapamycin (mTOR) signaling-determined tumor resistance toward alkylating chemotherapy." (PMID 30245855, 2018). "There was a positive relationship between SLC7A5 and MYC, mTOR and ATF4 (p < 0.001) and the positive relationship between MYC, HIF2A and SLC7A5 was only observed in luminal B tumours (p = 0.01 and p < 0.001, respectively)." (PMID 29566741, 2018). "Treatment of tumor-bearing mice with mTOR or MEK inhibitors effectively inactivated signaling and resulted in reduced proliferation and elevated apoptosis leading to tumor regression." (PMID 29872503, 2018). "The AKT signaling pathway is one of the major survival gateways of tumor cells, and growing evidence has showed that the over-active AKT/mTOR pathway promotes tumor cell survival." (PMID 30301881, 2018). "Our studies focus on the views that FBXW7 executes its tumor suppressor function by inhibition of EMT and the mTOR/p70S6K pathway, ensuring the efficiency of EGFR‐TKI treatment in NSCLC." (PMID 29633504, 2018). "In both CRLF2-re PDX, spleen weights were significantly reduced by ruxolitinib alone or when combined with mTOR inhibitors, and most pronounced in the BBT594/AZD2014 combination group, indicating significant reduction of total tumor burden." (PMID 29487712, 2018). "As we had previously shown in other human tumor cell lines, in the present work TXA1.HCl treatment also induced autophagy in NCI-H460 cells (inhibiting the mTOR pathway as observed by the decreased phosphorylation of P70S6K)." (PMID 30545153, 2018). "In tumor tissues, the expression levels of TRAF6, p-Akt, p-mTOR and p-p65 proteins were decreased in the TRAF6 shRNA groups compared with the control groups." (PMID 29703234, 2018). "Eicosapentaenoid acid and lycopene reduce tumor cell growth also by suppression of PIK3/Akt pathway and by further blocking the activation of downstream molecule mTOR." (PMID 30487390, 2018). "In this study, we first investigated mTOR regulation of PGAM1 expression and then the role of PGAM1 in mTOR-mediated glycolysis and tumor growth." (PMID 29362480, 2018). "The majority of the biomarkers studied are involved in tumor cell proliferation, of which HER2, EGFR, cyclin D, KI67 and MTOR were the most frequently reported." (PMID 30185893, 2018). "The mechanisms of action of GSK-3 are additional examples of biorhythms or Yin–Yang of immunity, playing as tumor suppressor or tumor promoter and involving pathways of PI3K/PTEN/Akt/mTOR, Ras/Raf/MEK/ERK." (PMID 29961900, 2018). "Along with the immune system, tumor vasculature is a key component of TME and can influence the tumor behavior and drug treatment; mTOR is involved in the regulation of tumor-related vascular formation, through the promotion of angiogenesis." (PMID 30126252, 2018). "Moreover, all five were positively correlated each other at a variable extent and were heterogeneously distributed within each tumor type category, supporting that they might interplay either as coexistent or alternative mechanisms in individual tumors in regulating mTOR gene expression." (PMID 29938004, 2018).
tumor (continued). "The data showed that the level of phosphorylated mTOR, AKT and S6 K1 were significantly higher in HCC tumor tissues than those of adjacent normal liver tissues." (PMID 29914442, 2018). "MK-2206 consistently resulted in the reduction of AKT and its downstream, mTOR, signalling pathways in PC3 and HT29 cells and tumours confirming the mechanism of action." (PMID 30377337, 2018). "It has been widely reported that PI3K/AKT/mTOR, MAPK, and WNT/CTNNB1 pathways all play major roles in MPNST tumor initiation and progression." (PMID 30112810, 2018). "Other targets of miR-199a include the tumor-promoting p21 (RAC1) activated kinase 4 (PAK4), the mammalian target of rapamycin (mTOR) and c-Met, which have been described as tumor suppressors in the context of HCC." (PMID 29337905, 2018). "Intriguingly, some of these molecules are related to oncogenesis and tumour progression/metastasis, namely, HRAS, KRAS, TGFBR1, TGFBR2, RB1, ITGA6, ITGB4, mTOR, TSC2 and APLP2." (PMID 30258067, 2018). "Tumor cells resistant to GDC-0941, a PI3K inhibitor, exhibit an increased activation of the PI3K/AKT/mTOR signaling pathway and OGT expression in comparison to GDC-0941-sensitive cells." (PMID 30356686, 2018). "We further revealed that SALL1 tumor suppressor activity depended on its ability to recruit NuRD and that this molecular process was controlled by MAPK p38 and ERK1/2, and mTOR signaling pathways in cancer cells." (PMID 29625565, 2018). "In conclusion, our data on dactolisib anti-tumor efficacy obtained in in-vitro and in-vivo experiments suggest that the PI3K/mTOR inhibitor dactolisib can enhance the cytotoxicity of TMZ+RT treatment." (PMID 29416647, 2018). "In a previous study, a rapamycin-sensitive growth advantage in BNIP3-knockdown tumor xenografts was shown, suggesting that BNIP3 inhibits cell growth by suppressing the mTOR pathway." (PMID 30307949, 2018). "In these tumor cells, the cytosolic domains of PD-1 was found to interact with the eukaryotic initiation factor 4E and RPS6, promoting the phosphorylation of these mTOR effector proteins." (PMID 30105035, 2018). "Conversely, TGF-β represses mTOR signaling, both in mice and humans, to inhibit NK cell activation, suggesting an mTOR-dependent immune suppressive role for TGF-β in tumor microenvironment." (PMID 29662490, 2018). "Further investigation revealed that Tan IIA stalled tumor growth by inducing cell cycle arrest and autophagy, through the inhibition of PKC, Ras/MAPK, and PI3K/Akt/mTOR pathways." (PMID 29416003, 2018). "Investigations in the zebrafish model further showed disruption of ubtor gene upregulated the mTOR signaling and promoted HRAS(G12V) mediated tumor formation in intact animals." (PMID 30080879, 2018). "Its physiological role is related to brain embryogenesis, but fusion with other genes results in increased tyrosine kinase activity leading to tumor development through PLC, JAK-STAT, PI3K-AKT, mTOR, SHH, JUN-B, CRKL-C3G, RAP1, GTPase and MAPK cascades." (PMID 29455659, 2018). "While the tumors’ transcriptional responses to ibrutinib and idelalisib were similar, larger differences existed between each tumor’s response to BCR inhibitors, selumetinib (MEK) and everolimus (mTOR)." (PMID 29227286, 2018). "Among its components, mTOR downstream of PI3K/Akt acts as a key kinase in this pathway, which mainly regulates the biological effects of tumor cell proliferation, growth, survival, and angiogenesis." (PMID 30104473, 2018). "Compared with the paired non-tumor liver tissues, significant up-regulation of CCRK, p-GSK3βSer9/GSK3β, p-mTORSer2448/mTOR, p-4E-BP1Thr37/46/4E-BP1, p-S6KThr389/S6K, mSREBP1, G-CSF, p-STAT3Tyr705/STAT3, and AR were detected in HCC tissues (p < 0.05)." (PMID 30523261, 2018). "Hence, big hopes were raised when anti-tumor activity could be attributed to mTOR-Inhibitors." (PMID 29659588, 2018).
tumor (continued). "Adaptation and survival of tumor cells in such a heterogenic microenvironment requires the coordination of several stress response pathways including HIF-1, mTOR, UPR, and autophagy." (PMID 30250843, 2018). "While AMPK is generally viewed as a tumor suppressor partly by phosphorylating TSC2 and Raptor, leading to inhibiting mTOR signaling, it can also display tumor-promoting activity by regulating NADPH and ROS levels in breast cancer." (PMID 30413706, 2018). "ATO induces autophagic cell death in several types of tumor cells, and degrades PML/RARα protein via mTOR pathway-mediated autophagy in APL cells." (PMID 29362482, 2018). "To summarize, we, for the first time, confirmed that CD300A promoted tumor progression by increase PECAM1 and ADCY7 expression, and activating the AKT/mTOR signaling pathway in AML." (PMID 29938007, 2018). "Tumor Microarrays were successfully stained for p-ER, EGFR, p-ERK1/2, p-mTOR, and IGF1R, and scored by a breast pathologist." (PMID 29486734, 2018). "Lastly, ubtor gene disruption in zebrafish increases mTOR activity and aggravates HRAS(G12V) induced neoplasia in the intact animals." (PMID 30080879, 2018). "In multiple myeloma xenograft mice models, MTF treatment (250 mg/kg daily) substantially sustained the in vitro findings by reducing tumor size, increasing expression of p-AMPK, and decreasing expression of p-mTOR and Ki67." (PMID 30241339, 2018). "AOE-reprogrammed tumours also showed reduced activation of the AKT and mTOR pathways, which pointed to a quiescence phenotype, rather than senescence." (PMID 29662623, 2018). "The combined inhibition of PI3K, AKT and mTOR ensures the dephosphorylation of the essential downstream targets S6K1, 4E-BP1 and AKT and is required for an effective and sustained reduction in tumor growth." (PMID 29357370, 2018). "However, our data support the concept that miR-100 may be responsible for inter-individual heterogeneity of mTOR expression in specific tumor types and even for the occurrence of dynamic changes of mTOR expression (and responsiveness to mTOR inhibitors) in individual patients." (PMID 29938004, 2018). "Such inhibition on the tumor growth was synergistically strengthened in miR-497 and miR-99a co-expressing group via synergistically suppressing IGF1R and mTOR, which is consistent with the observation in the in vitro assay." (PMID 28624790, 2017). "The extrinsic signaling pathway is activated by interferon-γ (IFN-γ) produced by TILs, resulting in JAK/STAT activation in tumor cells, and the intrinsic pathway is activated by PI3K/AKT/mTOR signaling." (PMID 29029502, 2017). "As the major upstream regulator of HIF-1α expression, EGFR/PI3K/AKT/mTOR and MAPK/ERK1/2 pathways were simultaneously suppressed by F2 in U87 cells and xenograft tumor model." (PMID 29156717, 2017). "Accordingly, the purpose of this study is to investigate the impact of molecular target agents on the tumor stroma of RCC and examine the efficacy of combination therapy with an mTOR inhibitor and a multiple‐tyrosine kinase inhibitor." (PMID 28834289, 2017). "In this study, we found that afatinib exhibited anti-tumor efficacy in vitro and in vivo by inducing apoptosis and blocking EGFR-mediated PI3K/AKT/mTOR signaling." (PMID 27902463, 2017). "Accumulating data demonstrate that anomalies in protein synthesis downstream of mTOR, at the expression level of 4E-BP1, play an important role in tumor formation." (PMID 28891980, 2017). "In summary, PLZF activates REDD1 expression and inhibits mTOR activation; KLK4 expression blocks PLZF-mediated REDD1 expression that results in activation of mTOR signaling, giving rise to tumor growth." (PMID 29050363, 2017). "Ursolic acid, a pentacyclic triterpenoid known for its anti-tumor effects, increased the expression of LC3-II, an autophagosome marker, and induced autophagy via the Beclin-1 and AKT/mTOR pathways." (PMID 29209152, 2017).
tumor (continued). "For example, MYC-driven tumor cells are highly dependent on ribosome biogenesis and protein synthesis, requiring a collaboration between MYC and mTOR signaling to satisfy the increased biosynthetic needs." (PMID 28443281, 2017). "Tumor analyses corroborated with in vitro data as autophagic induction indicated by increased LC3B and diminished mTOR (negative regulator of autophagy) levels were observed in euglenophycin-treated HCT116 xenografts." (PMID 29262645, 2017). "In this study, we used patient-derived cells and a radiation-resistant cell line in vitro and in vivo for two purposes: evaluate the anti-tumor effects and understand the mechanisms in the dual PI3K/mTOR signaling pathway regulation of radiosensitization." (PMID 28978144, 2017). "mTOR signaling pathway plays a central role in regulating cell proliferation and metastasis, and drives EMT in tumor cells." (PMID 28455969, 2017). "IHC staining of both p-mTOR and p-AMPK was confined to the tumor cell membrane and cytoplasm, with minimal staining of the surrounding connective tissues." (PMID 28257034, 2017). "Since PI3K/AKT/mTOR pathway is active in SCLC cell lines, we further examined the anti-tumor activity of RAD001 and BEZ235 in a panel of SCLC cell lines." (PMID 29290965, 2017). "Everolimus is an orally active mTOR inhibitor, and VEGF is a potent proangiogenic protein that plays an important role in tumor angiogenesis and acts by binding to the VEGFR on endothelial cells." (PMID 29074560, 2017). "In 81% of all analysed tumours PLD2 expression as well as phospho-Akt and mTOR activity were elevated while the expression of LKB1 was decreased." (PMID 28649994, 2017). "The addition of mTOR inhibitor RAD001 promotes autophagy and increases the radiosensitivity of tumour cells in an in vitro model." (PMID 28320471, 2017). "Similar results were reported of how simultaneous inhibition of pAKT expression and mTOR phosphorylation resulted in decreased survival of NSCLC cells and inhibition of tumor growth in vivo." (PMID 29234489, 2017). "ADAMTS9 functions as a tumor suppressor through decreasing cell proliferation and inhibiting angiogenesis via regulating AKT/mTOR pathway." (PMID 28503860, 2017). "The experiment was repeated using a mouse model and the observation of delay in tumour growth and involvement of PI3K-Akt-mTOR pathway validated the in vitro findings." (PMID 28320471, 2017). "We also demonstrate that high BIM protein expression positively correlated with increased sensitivity to the PI3K/mTOR and BCL-2/BCL-XL inhibitor combination, consistent with an ex vivo tumor slice study of single-agent ABT-737 treatment." (PMID 28848242, 2017). "GSEA performed on the ranked set of DEGs between SqCC and ADC TCGA tumour samples identified a significant enrichment of AKT and mTOR oncogenic signalling in SqCC, as defined by the oncogenic signature gene set." (PMID 28548087, 2017). "It is interesting to note that mTOR, TFEB, and molecules involved in intracellular protein trafficking such as Sec22b are found in tumor-derived MVs." (PMID 28993771, 2017). "In this study, we demonstrate that SH003-induced autophagy via inhibiting STAT3 and mTOR results in an induction of lysosomal p62/SQSTM1 accumulation-mediated reactive oxygen species (ROS) generation and attenuates tumor growth." (PMID 29179443, 2017). "mTOR inhibition significantly reduces VEGF and tumour vascularisation and complements docetaxel therapy." (PMID 28615679, 2017). "Collectively, these results indicated that the anti-tumor effect of Zey on HeLa and CaSki cells is tightly correlated with PI3K/AKT/mTOR and MAPK/ERK signaling pathways." (PMID 28490807, 2017). "PI3K/AKT/mTOR and JAK/STAT3 pathways play a vital role in tumor cell proliferation, and the inhibition of theses pathways contributes to apoptosis in tumor cells." (PMID 27564113, 2017).
tumor (continued). "Potential tumor-suppressing effects of sestrin 2 are thought to arise from its ROS detoxifying actions and its ability to regulate AMPK/mTOR signaling." (PMID 28525387, 2017). "The expressions of p-mTOR, p-S6, LDH-A and Gls were studied in control and Rapamune treated xenograft tumours (DAB-brown staining; magnification 400X) (PDF 209 kb)." (PMID 28578659, 2017). "We previously demonstrated that miR-99b-5p is a tumor suppressing miRNA in metastatic CRC, and that its suppressive effects are mediated chiefly by suppressing mTOR expression." (PMID 28415758, 2017). "For instance, in PTEN (+/−) deletion-driven tumor mouse models, down-regulation of LKB–AMPK expression resulted in a drastic acceleration of tumorigenesis through activation of mTOR." (PMID 28629173, 2017). "Functional assay revealed that ectopic expression of miR-497 or miR-99a in HCC cells resulted in a significant inhibition on tumor growth and invasiveness in vitro and tumor development in vivo via repressing the expression of IGF1R and mTOR." (PMID 28624790, 2017). "In conclusion, ponatinib exhibits anti-tumor efficacy in NB by inhibiting FGFR1 signaling and blocking the activation of PI3K/AKT/mTOR and JAK/STAT3 signaling pathways, as evidenced by both in vitro and in vivo assays." (PMID 27564113, 2017). "In another study, co-targeting mTOR with cetuximab, a monoclonal antibody targeting EGFR that acts upstream of both Akt and ERK pathway, prevented the growth of HNSCC tumor xenografts by decreasing cell proliferation and lymphangiogenesis." (PMID 28822012, 2017). "The tumor suppressors Tsc1 and Tsc2 form the tuberous sclerosis complex (TSC), a regulator of mTOR activity." (PMID 29127155, 2017). "AKT has pleiotropic oncogenic functions that include inhibition of multiple tumor suppressors, such as FOXO1/FOXO3A, Bad, p27, and GSK3β, and promotion of other oncogenic pathways, such as mTOR, p70S6K1, Rac, and survivin." (PMID 29088759, 2017). "This activation leads to phosphorylation of STAT1, STAT3, STAT5, ERK1/2, AKT and mTOR and goes on to drive EMT and promote invasion, migration, and proliferation for tumor progression." (PMID 28223541, 2017). "In conclusion, the major finding of our study is that miR-497 and miR-99a synergistically target IGF1R and mTOR, thereby impeding the HCC tumor growth." (PMID 28624790, 2017). "On the other hand, GBM cells have been demonstrated to withstand mTOR inhibition by activating glutamine metabolism via glutaminase (GLS) and combined mTOR and GLS inhibition results in synergistic tumor growth inhibition in a GBM preclinical setting." (PMID 29179732, 2017). "More recently, hypoxic TAMs have been shown to upregulate the expression of REDD1, a negative regulator of mTOR hindering glycolysis and angiogenic response revealing a functional link between TAM metabolism and tumor angiogenesis." (PMID 28447025, 2017). "Akt phosphorylates and inhibits the tumour suppressor TSC2 and thereby indirectly activates RHEB, which in turn is a positive regulator of mTOR." (PMID 28417948, 2017). "Elevated AKT/mTOR activity and HIF-1α expression were also evident in SqCC cells and xenograft tumours." (PMID 28548087, 2017). "At 25 days, the tumor volume and weight were markedly decreased in miR-99a or miR-497 over-expressed tumors compared to the control as IGF1R and mTOR were down-regulated in the xenograft tumors." (PMID 28624790, 2017). "In addition, application of the mTOR inhibitor rapamycin reduced BaP-induced lung tumor formation, growth, and progression in A/J mice; however, the role of this signaling in BaP-induced tumor formation remains unclear." (PMID 27858113, 2017). "In agreement with our in vitro data, +TAM tumor sample showed an increased level of YAP1, Kras, Akt/mTOR, NF-kB (oncogenic markers), and β-catenin (both oncogenic and stemness marker)." (PMID 28241877, 2017).